IL6 (interleukin 6)
Diseases named in the same sentence as IL6 in open-access papers (continued):
Sharing a sentence is not in itself a finding about the gene and the disease.
tumor (continued). "Moreover, cytokines regulated by STAT3 in tumor microenvironment, like IL-6, IL-10, VEGF and TGF-β, trigger a positive feed-back amplification of STAT3 in multiple types of cells throughout the tumor microenvironment, finally resulting in severer tumor growth and immuno-suppression." (PMID 34502195, 2021). "However, IL-6 staining in tumor epithelial cells was also observed in ∼44% of tumors." (PMID 33851955, 2021). "Inhibiting the expression of PD-1 in tumors leads to increased levels of IL-6 and IL-17 in the peripheral blood; because the main function of IL-6 and IL-17 is to promote neutrophil-mediated inflammation, this may weaken the anti-tumor immune response." (PMID 34290608, 2021). "Thus, IL-6 serves as a key link between chronic inflammation and tumor progression." (PMID 34445405, 2021). "However, IL-6 neutralization moderately enhanced the ratios of CD8+ T cells in tumor-associated CD45+CD3+ T cells, but did not activate these T cells, as indicated by no increases detected in Ki67+, IFN-γ+, or CD69+ activating T cells in CD45+CD3+ T cells." (PMID 34103524, 2021). "Also, crosstalk between human and murine IL6 pathways in the murine tumor microenvironment by tumor-infiltrating immune cells or fibroblasts can potentially prime the metastatic niche and hyperactivate STAT3 pathways in cancer cells through IL6 trans-signaling pathways." (PMID 34262028, 2021). "Thanks to the production of pro-inflammatory factors, such as CCL2, IL-8, CCL3, and IL-6, and their crosstalk with activated T cells, TANs, in early-stage human lung cancer, are actively involved in the stimulation of T cells responses limiting tumor progression." (PMID 33418996, 2021). "Moreover, blocking the crosstalk between tumor-educated MSCs and tumor cells using IL6- and TGFβ inhibitors may also represent useful therapeutic options to be explored in the future." (PMID 34198693, 2021). "Moreover, the tumor area was also significantly larger in the combined Bev and anti-IL-6-treated group than in the groups treated with Bev alone (p = 0.002), suggesting that IL-6 blockade disrupted both the anti-angiogenic and concomitant anti-tumor effects of Bev." (PMID 33833265, 2021). "Another benefit to tumor cells from S100B-dependent inhibition of IL6 secretion could be to prevent IL6 activation of B cells, T lymphocytes, and dendritic cells as a means to avoid an anti-tumor immune response at an early stage or in regions with little or no signs of a stress-response." (PMID 34411141, 2021). "In biliary tract cancers, differential secretion of TGF-β1 and IL-6 is one of the main causes of the heterogeneous distribution of Treg and Th17 cells in the TME, with the tumor center enriched in the Treg subpopulation, and the tumor invasion front mainly represented by Th17 cells." (PMID 34439114, 2021). "However, in human tumor cells, IL-6 alone can significantly upregulate the enzyme expression." (PMID 34394118, 2021). "Previous research demonstrated that M2 macrophages could secrete several immune suppressors such as IL-10 and TGF-β and could downregulate IL-12 and IL-6, contributing to the suppression of T-cell activation and proliferation in tumor microenvironment, as well as inducing the infiltration of Tregs." (PMID 34650972, 2021). "IL-35 has been shown to promote N2 neutrophil polarization by increasing G-CSF and IL-6 production, thereby enhancing the ability of these N2 cells to promote angiogenesis and to suppress immune responses, thereby enabling invasion of N2 cells into tumor tissue." (PMID 34093586, 2021). "Increased levels of IL-6 have been observed with BLCA patients, and an activated cytokine IL-6 signaling provides a suitable microenvironment for CD44 induction where in immunocompetent mouse models blockade of IL-6 decreased CD44 expression attenuating tumor aggressiveness." (PMID 33672684, 2021).
tumor (continued). "The study aimed at assessing whether curcumin induces apoptosis of RCC and the involvement of AKT/mTOR pathway, the effects of curcumin on pro-inflammatory TNF-a, IL6 and IL-8 cytokines, and finally, to understand the role of curcumin in autophagy and tumor-growth in vivo." (PMID 34402718, 2021). "Consequently, tumor cells might stimulate the production of osteoblast-derived cytokines including IL-6, which results in increased osteoclast differentiation and subsequent bone destruction." (PMID 33809315, 2021). "Interestingly, in this model, IL-6 not only recruits NK cells that limit tumor growth, but also reinforces the senescence phenotype through autocrine and paracrine mechanisms, indicating that bystander (initially) non-senescent tumor cells can be targeted as well." (PMID 34079557, 2021). "Similarly, doxorubicin treatment had significant inhibition of PDAC tumor growth in IL-6 KO mice." (PMID 34711820, 2021). "Furthermore, MYDGF can also promote tumor angiogenesis, induce macrophages to chemotaxis into tumor tissue, and then release various inflammatory cytokines, including IL-6 and TNF-α, which ultimately aggravate inflammation of tumor microenvironment and accelerate HCC progression." (PMID 33391471, 2021). "Here, we evaluated the exposure–response of efficacy (cytotoxicity) versus safety (IL6 release) with the integrated analysis in the same high-expressing cell line (MKN45) as previously utilized to ensure the safety of patients with high tumor target expression." (PMID 34862519, 2021). "Notably, Osmrhigh CAFs express higher levels of inflammatory signals such as Il6, Ccl7, Ccl2 and Cxcl1 in animal models of PDA, OSMR is expressed at increased levels in human PDA and is associated with a tumour-promoting immune infiltrate and worse patient outcome." (PMID 34921158, 2021). "Interestingly, among the differentially expressed antigens found by us, IL-6 has already been described as a tumor-discriminating antigen in PCa, while high levels of PD-L1, Integrin-β5 and Survivin upregulation seems to correlate with cancer survival and aggressiveness." (PMID 34155195, 2021). "Furthermore, tumor releases GM-CSF and IL-6 promotes the conversion of myeloid cells to an MDSC phenotype, mainly through the activation of a CCAA T-enhancer-binding protein β(C/EBP β)-mediated program that implicates the downstream blockade of STAT3 for terminal differentiation." (PMID 34527668, 2021). "Additionally, MYDGF could induce the chemotaxis of macrophages into tumor tissues and promote them releasing inflammatory cytokines, including IL-6 and TNF-α." (PMID 33391471, 2021). "A different approach which may improve fine-tuning of anti-tumor responses following PCV treatment is the removal of non-productive inflammation caused by interleukin 6 (IL-6)." (PMID 34335558, 2021). "Interestingly, IL-6 is exploited by GC tumour cells to aid in their proliferation." (PMID 34944729, 2021). "Moreover, IL-6 may also resculpt the T cell immune response, shifting it from a suppressive to a responsive state that can effectively act against tumours." (PMID 33923108, 2021). "Given the increase in production of IL‐1β, TNF‐α, IL‐12, IL‐22, and IL‐6 by the expanded inflammatory Ly6C+MHCII+ monocyte population in the tumor following the administration of SL7207, it was hypothesized that monocyte populations may underpin the tumor‐growth inhibition effects of SL7207." (PMID 34633664, 2021). "Consequently, the ultimate impact of IL-6 on the generation of anti-tumor immune responses in vivo remains unclear." (PMID 34711820, 2021). "However, the slight reduction of IL6ST observed in many tumors may partially affect the direct action of IL-6 on tumor cells." (PMID 34576335, 2021).
tumor (continued). "Preventing CARD10 cleavage in the lung tumor A549 cell line increased basal levels of IL-6 and extracellular matrix components in vitro, and led to increased tumor growth in a mouse xenograft model, suggesting that CARD10 cleavage by MALT1 might be a built-in mechanism controlling tumorigenicity." (PMID 33824280, 2021). "This transient elevation of IL-6 seems beneficial, as it promotes skeletal muscle glucose uptake and in the context of cancer, might help the immune system inhibit tumor growth." (PMID 33801684, 2021). "Firstly, macrophage markers IL6, CSF1R, CXCL12 were weak-to-strong positively associated with NEFM expression, which could reveal a potential role of NEFM transcriptional expression in regulating polarization of tumor-associated macrophage (TAM)." (PMID 34001208, 2021). "Moreover, IL-11 is present in larger amount in cancer compared to IL-6 and, thus, it may play a relevant role in neoplastic disease." (PMID 34201209, 2021). "Finally, our results further show that STAT3 activation was elevated in the immune cells exposed to PARP inhibitor-resistant tumor cells, which was contributed by an increase in IL-6 expression by Olaparib-resistant OVCAR8 cells relative to their parental counterparts." (PMID 34956861, 2021). "This case implied that IL-6 is not necessarily the cause of tumor growth in AFH." (PMID 34221525, 2021). "This CTNNB1 gene mutation has been associated with the inflammatory subtype of tumor hepatocytes, which is characterized by an over expression of acute phase inflammatory proteins like CRP and serum amyloid A (SAA) and the consequent constitutive activation of the IL6/JAK/STAT pathway." (PMID 34503196, 2021). "Additionally, research showed that IL6 were highly secreted in tumor cell/fibroblast co-cultures." (PMID 34960256, 2021). "Within the tumor stroma, IL-6 may also act to promote tumor evasion and angiogenesis." (PMID 34439305, 2021). "Furthermore, these results implicate that IL-6 blockade may represent a strategy to activate T-cell-based anti-tumor immunity." (PMID 34103524, 2021). "Finally, we observed that stromal factors such as IL-6 and IL1B may underlie the different effects of the involvement of MMP2-positive BMDCs in tumor invasion." (PMID 35008304, 2021). "However, several factors including tumor heterogeneity, epigenetic regulation by miRNAs, synergistic effects of multiple signaling pathways such as Akt/PI3K, MAPK/ERK, NF-κB/IL-6, mTOR, Hedgehog, and somatostatin receptor have been shown to contribute to drug resistance in these tumor cells." (PMID 33805398, 2021). "Therefore, we administered doxorubicin and dexamethasone to tumor-bearing IL-6 deficient mice but failed to see any significant negative effect on anti-tumor immunity." (PMID 34711820, 2021). "In addition, there is an increased release of pro-inflammatory cytokines, such as IL-22 and IL-6, early after TACE treatment; and in patients with larger tumours (>5 cm) there is an early increase in IL-6 and a late increase in IL-4, IL-5, and IL-10 after TACE treatment." (PMID 34884853, 2021). "Moreover, the cytokine IL-6 produced in the microenvironment exerts a pro-tumor activity." (PMID 35096626, 2021). "A series of reports have shown that IL6 trans-signaling plays a major role in the immune response of the tumor cells by activating T-lymphocytes, promoting T-cells trafficking to the lymph nodes, transmigration of T lymphocytes into tumor tissues, and B-cells activation." (PMID 34411141, 2021). "In addition, exosomes derived from tumour cells could be able to make MDSCs secrete inflammatory cytokines such as IL‐6 and TNF‐α, which further promoted the expansion of MDSCs." (PMID 33955151, 2021). "Similar to IL-6, IL-17 may induce tumour growth through an IL-6-Stat3 signalling pathway." (PMID 33923108, 2021).
tumor (continued). "In addition, API can suppress the signaling pathway due to IL-6 which is responsible for chronic inflammation associated with breast cancer, for instance, and responsible for the EMT process, the invasion and migration of tumor cells." (PMID 34572548, 2021). "We have previously reported that the presence of >1% of IL-6 + non-malignant cells in the tumor microenvironment is associated with poor prognosis in cHL, hence aligned with current study result, identifying IL-6 as a distinguishing cHL protein increased in cHL tissues." (PMID 35008176, 2021). "For example, aberrant EGFR signaling in NSCLC cells upregulates PDL1 expression through activation of the IL6/JAK/STAT3 pathway, while combined STAT3 and PDL1 inhibition renders tumor cells more susceptible to cytotoxic T-cell mediated killing and delays tumor growth in mice." (PMID 34944848, 2021). "Finally, we compared the OS of this group (13 patients) to the group of patients bearing a tumor with high stromal IL-6 and low cancer cell LC3 (n = 7) and the group of patients bearing a tumor with other combinations (n = 10), and again the former group showed a better survival rate (p = 0.018)." (PMID 33925189, 2021). "Among the target genes of IL-6 is IL-8, a member of the C-X-C family of chemokines that plays a central role in inflammation, angiogenesis, and tumour growth, with the IL-8 receptors expressed on several cell types like neutrophils, monocytes, endothelial cells, and tumour cells." (PMID 34956228, 2021). "In addition, the blockade of type 1 immune response, elevation of Treg cells, expansion of MDSCs, and activation of stromal fibroblasts could also be induced by IL-6, thus contributing to tumor development." (PMID 34497832, 2021). "In addition to their well described role in immunosuppression, MDSC have also been shown to confer stem-like phenotypes to tumor cells through various mechanisms including MDSC secretion of IL-6, activation of STAT3 or induction of miRNA expression in tumor cells." (PMID 33805598, 2021). "Finally, by using the same 3D microfluidic cultures, we evaluated the efficacy of a therapy against one of the identified inflammatory cytokines to impair metastasis formation induced by the local tumour acidosis: anti-IL6 antibody completely impaired OS migration." (PMID 34831016, 2021). "In addition to the main contents of pyroptotic production, intrinsically, another member, IL‐6, is found to play a role in tumor cells by supporting malignant progression including proliferation, metastatic dissemination, and survival by connecting with numerous downstream mediators." (PMID 34459122, 2021). "Similarly, senescent fibroblasts through the secretion of IL-6/IL-8 and amphiregulin were shown to favor the differentiation of monocytes into proinflammatory M2 macrophages and to drive the expression of PD-L1 in tumor cells, respectively." (PMID 34206425, 2021). "We observed that, while C91/PL cells did not change their release in this cytokine, HFF and the coculture showed a significant increase in IL-6 in the supernatants at 48 h, suggesting that this increment might have counterbalanced the initial delay in tumour development in vivo." (PMID 34638901, 2021). "Also, IL‐6 is also important for enhancing T cell trafficking to lymph nodes and the tumor sites." (PMID 34459122, 2021). "The secreted proteins CCL2, TNFRSF21, PLC, COL1A1, PlGF, PAI and IL-6 are all known to be involved in cancer progression and have pro-tumorigenic properties, suggesting that cancer cells can be shifted towards a more aggressive state by tumor microenvironmentally induced secretion." (PMID 34090457, 2021). "Loss of IL-6 and use of inhibitors of STAT3 and MEK/ERK pathways suppress tumorigenesis in 3D organotypic and tumoroid models, showing how STAT3 and MEK/ERK pathways are also solicited in crosstalk between tumour cells and GCAFs for the maintenance of tumour integrity." (PMID 33810350, 2021).
tumor (continued). "Autocrine or paracrine IL-6 signaling may fuel the tumor growth." (PMID 35008292, 2021). "In addition IL6 was mainly secreted by tumor cells in the co-culture system; therefore, we hypothesized that IL6 would be involved in GSC self-renewal and would mediate the effects of TGF-β on GSCs." (PMID 33576874, 2021). "Likewise, resident cells such as lymphocytes, macrophages, fibroblasts, and tumor cells themselves may produce VM-promoting factors including the inflammatory cytokines IL-6, IL-8, TGFB, and IL-1β." (PMID 34359928, 2021). "We focused on EVs as factors that may be contained in tumor CM and induce IL-6 upregulation in ECs." (PMID 34226586, 2021). "Moreover, TNF-α derived from TAMs could stimulate tumour cells to release IL-6, contributing to STAT3 activation in TAMs." (PMID 33654093, 2021). "Given that these cytokines were found to be crucial for triggering the expansion (GM-CSF and IL-6) or pathologic activation (IFN-γ and IL-6) of MDSCs in studies with tumor tissue or BM stroma, the splenic microenvironment of sanroque mice may be sufficient to serve as a niche for SDMCs." (PMID 33643317, 2021). "Numerous inflammatory mediators such as TNF-α, IL-6, IL-10, IL-23, and transforming growth factor-β (TGF-β) were found to be associated with carcinogenesis and the development of CRC and their effects include pro-tumor, anti-tumor, and double-edge effects in CRC pathogenesis." (PMID 33578830, 2021). "Furthermore, the interleukin 6 (IL6)-induced tumor sphere formation was reduced by RPS6-KD." (PMID 35008473, 2021). "Stromal-derived factors (such as IL-6) could favor the migration of myeloid cells, altering their differentiation into fully functional dendritic cells (DCs) and upregulating PD-L1; thus, PD-L1+ myeloid cells can suppress T cells in the tumor microenvironment." (PMID 34945784, 2021). "Therefore, IL-6 signaling seems to be a promising target in anti-tumor therapy." (PMID 34681685, 2021). "Blocking the IL-1β/IL-6 network in TME could halt tumor progression." (PMID 34379689, 2021). "Moreover, GSEA results indicated that the IL6/JAK/STAT3/SIGNALING pathway could be considered as a potential mechanism of genomic instability to influence tumor progression." (PMID 34712264, 2021). "Besides, one study discovered that Cetuximab could also enhance the anti-tumor function of macrophages through IL-6 pathway." (PMID 34717710, 2021). "Our results suggest that IL-6 is a key regulator of anti-cancer immune responses induced by genotoxic stress and that its inhibition can switch cancer cell clearance from primarily apoptotic to immunogenic, promoting and maintaining durable anti-tumor immune responses." (PMID 34711820, 2021). "One study demonstrated that IL-6 secretion could upregulate programmed cell death-ligand 1 (PD-L1) expression in neutrophils, thus inhibiting the activity of T cells and ultimately accelerating the immune escape of tumor cells." (PMID 34976809, 2021). "Furthermore, anti-IL-6 antibodies reduced the tumor NK cell infiltration." (PMID 34068618, 2021). "Interestingly, the production of IL-6 increased in the tumor, spleen, and brain." (PMID 34572719, 2021). "Interestingly, this result indicated that the IL6/JAK/STAT3/SIGNALING pathway may be a potential pathway for explaining how genomic instability-derived lncRNAs affected tumor progression." (PMID 34712264, 2021). "Finally, our studies suggest that strategies as diverse as targeting tumor cell production of IL-6, IL6R shedding from muscle and other tissues, adipose lipolysis, or lipid uptake by muscle might each show benefit in PDAC." (PMID 33851955, 2021). "Therefore, recent data suggests that IL-6/JAK/STAT3 signaling pathway may represent a therapeutic target to suppress tumor growth and activate the antitumor immune response." (PMID 33080912, 2020).